EPHA5 (EPH receptor A5)
Diseases named in the same sentence as EPHA5 in open-access papers (continued):
Sharing a sentence is not in itself a finding about the gene and the disease.
squamous cell carcinoma (3 papers, 2014 to 2020). A carcinoma arising from squamous epithelial cells. "Among 10 ESCC patients with high expression of EphA5, there were 7 patients with advanced tumor stage (T3 and T4), 8 patients with positive lymph nodes, and 9 patients with moderately differentiated squamous cell carcinoma." (PMID 31956298, 2020). "Thus, we conclude that high EphA5 expression is correlated with regional lymph node status, advanced tumor stage and moderately differentiated squamous cell carcinoma." (PMID 31956298, 2020). "Additionally, increase of EphA5 expression was more often found in the ESCC patients with moderately differentiated squamous cell carcinoma." (PMID 31956298, 2020).
cervical cancer (2 papers, 2018 to 2025). A primary or metastatic malignant neoplasm involving the cervix. "Furthermore, EPHA5 has been implicated in various malignancies, including cervical cancer, where integrative transcriptomic analyses identified it as part of oncogenic signaling networks that regulate proliferation, migration, and immune responses." (PMID 40806980, 2025). "In cervical cancer, integrative transcriptomic meta-analyses identified EPHA5 among a panel of dysregulated genes involved in tumorigenesis." (PMID 40806980, 2025).
Depression (2 papers, 2019 to 2025). "Common variants in MTR, PPARA, ABCC3, CALML5, CACNB2 and PCDHB10 genes were associated with deficits in neurocognitive tests performance, whereas a variant in SLCO1B1 and EPHA5 genes was associated with anxiety and depression." (PMID 31181069, 2019). "The carriers of the minor C allele of EPHA5 rs33932471 were at higher risk of both moderate-severe anxiety and depression, with the strongest effects seen in females (p = 0.02 and p = 0.003, respectively)." (PMID 31181069, 2019). "The rs11556218 in the EPHA5 gene was associated with higher risk of both anxiety and depression that was further potentiated in female patients." (PMID 31181069, 2019). "Functionally predicted germline common variants in MTR, PPARA, SLCO1B1, ABCC3, CALML5, CACNB2 and PCDHB10 genes were found to be significantly associated with deficits in neurocognitive tests performance, whereas a variant in EPHA5 gene was significantly associated with both anxiety and depression." (PMID 31181069, 2019).
esophageal cancer (2 papers, 2020). A primary or metastatic malignant neoplasm involving the esophagus. "Therefore, this study aimed to investigate the roles of EphA5 in ESCC and the mechanism by which EphA5 regulates ESCC cells, its association with metastasis and prognosis of patients with esophageal cancer." (PMID 31956298, 2020). "The results showed that EPHA5, LOC100506136, RGS7, THBS4, SCGB1A1, and DPEP1 were dysregulated between esophageal cancer and normal control in GSE13898 validation dataset (all, P<0.05)." (PMID 32068233, 2020). "This current study shows that EphA5 is differentially expressed in esophageal cancer samples but not expressed in the squamous epithelium of the paracancerous normal tissues." (PMID 31956298, 2020).
esophageal squamous cell carcinoma (2 papers, 2020 to 2025). Esophageal squamous cell carcinoma (ESCC) is a type of esophageal carcinoma (EC) that can affect any part of the esophagus, but is usually located in the upper or middle third. "EphA5 knockdown promotes the proliferation of esophageal squamous cell carcinoma,enhances invasion and migration ability via epithelial-mesenchymal transition through activating Wnt/β‐catenin pathway." (PMID 31956298, 2020). "However, the role of EphA5 in esophageal squamous cell carcinoma (ESCC) is not clear." (PMID 31956298, 2020).
lymph node metastasis (2 papers, 2020 to 2025). "But the association between EphA5 expression and regional lymph node metastasis or nerve and vascular invasion was not analyzed." (PMID 31956298, 2020).
myeloma (2 papers, 2017 to 2020). "Moreover, a six-gene risk score model (ZNF486, EPHA5, RP11.326C3.15, DUSP6, DUSP10, and TRIAP1) for the prognostic prediction of PI-treated myeloma patients was developed by the random survival forest variable hunting (RSF-VH) algorithm." (PMID 33344452, 2020).
pancreatic adenocarcinoma (2 papers, 2020 to 2024). "In pancreatic adenocarcinomas, patients with moderate or high EphA5 and EphA7 expression had shorter survival times compared to the low-expression group." (PMID 33007931, 2020). "For example, heightened EphA5 expression correlated with an unfavorable prognosis of papillary renal cell carcinoma (KIRP) and uveal melanoma (UVM), whereas predicting improved survival in pancreatic adenocarcinoma (PAAD)." (PMID 38952552, 2024).
schizophrenia (2 papers, 2023). A major psychotic disorder characterized by abnormalities in the perception or expression of reality. "In a recent study investigating the molecular organization of human dorsolateral prefrontal cortex, two schizophrenia risk genes, membrane-bound ligand ephrin A5 (EFNA5) and ephrin type-A receptor 5 (EPHA5), were identified to colocalize via cell-cell communication analysis." (PMID 36993732, 2023).
serous carcinoma (2 papers, 2016 to 2021). "Downregulation of EPHA5 seems to contribute to carcinogenesis, since from normal fallopian tissues and benign ovarian neoplasms to borderline tumors and serous carcinomas, a progressive loss of EPHA5 expression was noted." (PMID 34445116, 2021).
uveal melanoma (2 papers, 2020 to 2024). A melanoma derived from melanocytes of the uveal tract. "The aim of the study was to evaluate the expression of ephrin receptors EphA1, EphA5, and EphA7 in uveal melanoma and its associations with clinicopathological parameters, overall survival, and disease-free survival." (PMID 33007931, 2020). "The present study documented for the first time that some uveal melanomas express EphA1, EphA5, and EphA7 receptors." (PMID 33007931, 2020). "The present study aimed to assess EphA1, EphA5, and EphA7 expression in uveal melanoma, combined with clinicopathological parameters, overall survival, and disease-free survival." (PMID 33007931, 2020). "Kaplan–Meier survival curves indicated that uveal melanoma patients with high EphA5 expression presented significantly longer overall survival periods compared to those presenting low EphA5 expression (p = 0.031)." (PMID 33007931, 2020). "In uveal melanoma, as with EphA1, high EphA5 expression is also a favorable prognostic factor." (PMID 33007931, 2020).
Alzheimer disease (1 paper, 2022). A progressive, neurodegenerative disease characterized by loss of function and death of nerve cells in several areas of the brain leading to loss of cognitive function such as memory and language. "Using the “rms” package (version 6.2-0) in R (version 4.0.2), a nomogram model based on the 3 specific genes (CARTPT, EPHA5, and SERPINA3) was constructed to predict the risk of Alzheimer's disease (GSE122063)." (PMID 35996379, 2022).
benign prostatic hyperplasia (1 paper, 2015). A non-cancerous nodular enlargement of the prostate gland. "In this study, we systematically evaluated the expression profile and methylation status as well as its clinical relevance of the EphA5 gene in prostate cell lines, benign prostatic hyperplasia, primary human prostate tumors, and paired noncancerous tissues." (PMID 25609195, 2015).
Candida infection (1 paper, 2025). "To elucidate the cellular mechanisms underlying the increased susceptibility of EphA5-deficient mice to Candida infection, we established a chimeric bone marrow model." (PMID 40489568, 2025).
cataract (1 paper, 2024). Partial or complete opacity of the crystalline lens of one or both eyes that decreases visual acuity and eventually results in blindness. "Moreover, Epha5 expression was decreased in Mafg–/–;Mafk–/– double knockout mice, a model that exhibits cataracts after 4 months of age." (PMID 38984128, 2024).
clear-cell renal cell carcinoma (1 paper, 2020). "In clear-cell renal cell carcinoma, a decrease in EphA5 expression is observed compared to healthy renal tubular epithelial cells." (PMID 33007931, 2020).
colon cancer (1 paper, 2025). "In most cases, the percentage of EphA5-expressing cancer cells per tissue section averaged 70% or higher, except for colon cancer, in which approximately 45% of cancer cells showed positive EphA5 staining." (PMID 40662373, 2025).
congenital hypothyroidism (1 paper, 2021). A thyroid hormone deficiency present from birth. "It has also been revealed that abnormal expression of EPHA5 affects synaptogenesis in congenital hypothyroidism rats during brain development." (PMID 33912567, 2021).
endometrial cancer (1 paper, 2025). Primary or metastatic malignant neoplasm involving the endometrium (mucous membrane that lines the endometrial cavity). "In conclusion, our study identifies EphA5 as a context-dependent biomarker in endometrial cancer, demonstrating paradoxical associations with proliferative and metabolic markers." (PMID 40806980, 2025). "This unexpected outcome raises questions about the underlying biology of EphA5 and suggests that its role in endometrial cancer may be more complex than previously understood." (PMID 40806980, 2025). "Background/Objectives: Eph receptor A5 (EphA5) is a receptor tyrosine kinase that is implicated in multiple malignancies, although its role in endometrial cancer (EC) remains unclear." (PMID 40806980, 2025). "Future translational research should explore EphA5 as a potential target or surrogate marker in precision oncology strategies for endometrial cancer." (PMID 40806980, 2025). "Our findings highlight a unique context-dependent role of EphA5 in endometrial cancer, particularly in relation to proliferative signaling and metabolic regulation." (PMID 40806980, 2025).
epilepsy (1 paper, 2017). A brain disorder characterized by episodes of abnormally increased neuronal discharge resulting in transient episodes of sensory or motor neurological dysfunction, or psychic dysfunction. "During the activation, various genes of our predicted EPH family have been identified to promote such biological processes, validating the crucial role of EPH family including our predicted genes EPHA3, EPHA4, EPHA5, EPHA7, and EPHB2 during epilepsy." (PMID 28255556, 2017).
fungal infection (1 paper, 2025). "Furthermore, histopathological examination and periodic acid-Schiff (PAS) staining revealed increased renal inflammation and a greater fungal load in the kidneys of EphA5-KO mice than in those of WT mice, indicating that EPHA5 deficiency exacerbates fungal infection and tissue damage." (PMID 40489568, 2025). "Here, we show evidence that, upon fungal infection, EPHA5 phosphorylates EPHB2 for its activation, which is critical for the activation of downstream signaling pathways." (PMID 40489568, 2025). "As EPHA5 cannot directly recognize β-glucan, the mechanism of EPHA5 activation after fungal infection still needs to be addressed in the future." (PMID 40489568, 2025). "Here, by using cellular and mouse fungal infection models, we report that EPHA5 is an upstream kinase for EPHB2 and Dectin-1 after fungal infection, which facilitates the subsequent activation of downstream antifungal signaling pathways." (PMID 40489568, 2025). "In the present study, we show that EPHA5 plays a critical role in the antifungal innate immune response by phosphorylating EPHB2 and Dectin-1 after fungal infection, which facilitates the recruitment and activation of Syk for downstream activation of antifungal signaling pathways." (PMID 40489568, 2025). "In this study, we show that EPHA5 plays a critical role in antifungal immunity by phosphorylating EPHB2 and Dectin-1 after fungal infection, which facilitates the recruitment and activation of Syk and subsequent activation of downstream antifungal signaling pathways." (PMID 40489568, 2025).
Hypoglycemia (1 paper, 2021). A decreased concentration of glucose in the blood. "The EPHA5 and CFTR proteins are both implicated as functioning in the ventromedial hypothalamus (VMH) at the level of synaptic neuron-glia in response to hypoglycemia by enhancing glutamatergic neurotransmission." (PMID 33572894, 2021).
Immunodeficiency (1 paper, 2025). Failure of the immune system to protect the body adequately from infection, due to the absence or insufficiency of some component process or substance. "To determine whether the increased susceptibility of the EphA5-KO mice was due to underlying immunodeficiency, we examined the distributions of major immune cell populations in the peripheral blood, lymph nodes, and spleen under steady-state conditions." (PMID 40489568, 2025).
ischemic stroke (1 paper, 2022). A stroke disorder caused by obstruction of blood flow to the brain, due to thrombotic (local blood clot formation) or embolic (due to a blood clot or other material traveling from another site) event. "Carmichael and coworkers injected EphA5-Fc-releasing hydrogels into the injured brain to inhibit EphA-signaling in neurons and found that EphA5-Fc promoted functional recovery of the subacute phase of ischemic stroke." (PMID 35666393, 2022).
mesothelioma (1 paper, 2024). A usually malignant and aggressive neoplasm of the mesothelium which is often associated with exposure to asbestos. "In summary, we found that the transcript levels of EGFR and MMP1 were downregulated, while EPHA5 and PARK2 were upregulated in response to YB‐1 knockdown using both siRNAs in mesothelioma cells." (PMID 36550787, 2024).
metastatic cancer (1 paper, 2020). A carcinoma which has spread from the original site of growth to another anatomic site. "Analysis of a few patients with metastatic cancer survive exceptionally longer than others under the same treatment identified multiple common mutations of NOTCH2, NF1, FANCD2, PIK3CB and EPHA5 in tumors that responded exceptionally well to treatments." (PMID 32600248, 2020).
ovarian epithelial tumor (1 paper, 2016). A benign, borderline, or malignant tumor that originates from the surface epithelium of the ovary. "The expression of EphA5 protein was determined in ovarian epithelial tumors and normal fallopian tube by immunohistochemical staining." (PMID 27887627, 2016).
pilocytic astrocytoma (1 paper, 2018). Pilocytic astrocytoma is a rare subtype of low-grade glioma of the central nervous system characterized by a well circumscribed, often cystic, brain tumor with a discrete mural nodule and long, hair-like projections that extend from the neoplastic astrocytes. "Histologic examination showed pilocytic astrocytoma (PA) with anaplasia, and molecular characterization revealed FGFR1 duplication with additional variants of unknown significance in several genes (ARID1A, ARID1B, CHEK2, EPHA5, and MLL2)." (PMID 29610389, 2018).
prostate tumors (1 paper, 2015). "Similar to the results of qRT–PCR in the corresponding tissues, EphA5 protein level in prostate tumour samples was significantly lower than that of matched adjacent normal tissues or BPH tissues." (PMID 25609195, 2015). "To further validate the expression of EphA5 in human PCa tissue, we also analysed 4 BPH tissues, 5 primary prostate tumors tissues and 4 paired normal tissues in our study by Western blotting assay." (PMID 25609195, 2015).
vitreous hemorrhage (1 paper, 2020). Blood extravasation in the vitreous humor. "Total high EphA5 expression was associated with less frequent loss of chromosome 3 (p < 0.001), absence of distant metastases (p = 0.010), and more frequent occurrence of vitreous hemorrhage (p = 0.013)." (PMID 33007931, 2020). "High expression of EphA5 was associated with less frequent chromosome 3 loss, absence of distant metastases, and more frequent vitreous hemorrhage." (PMID 33007931, 2020).
tumor (44 papers, 2012 to 2025). "Accumulating evidence reveals that EPHA5 mutations contribute to tumor immunity, tumor migration and invasion." (PMID 39925800, 2025). "Although high EphA5 expression correlates with elevated Ki-67 levels and reduced pAMPK expression—features typically linked to tumor aggressiveness—it is independently associated with favorable overall survival outcomes." (PMID 40806980, 2025). "EphA5 and EphA7 are associated with tumor growth, with higher expression correlating with shorter survival." (PMID 39839790, 2024). "EphA2 expression was significantly associated with patient age, while EphA4 and EphA5 with tumor proliferative capacity." (PMID 39839790, 2024). "The scenario was attributed to various mechanisms including correlation of EPHA5 mutations with enhanced tumor infiltrating lymphocytes (TILs), increased tumor mutational burden (TMB) and so on." (PMID 36123678, 2022). "A strong correlation between the mutations in EPHA5 and tumor immunity has been reported in studies." (PMID 36123678, 2022). "Loss of EPHA5 expression was associated with low tumor histological grade and poor patient outcome in various cancer types." (PMID 34331411, 2021). "To ensure that a sufficient number of patients with mutations were included in subsequent statistical analyses, we selected EPHA5, with a mutation frequency of higher than 10%, to examine the relationship of EPHA5 mutations with tumor immune microenvironment." (PMID 33288738, 2020). "EphA5 and A7 expression was significantly positively associated with tumor proliferative capacity (p = 0.006 and p = 0.028, respectively), while EphA4 expression showed a trend of correlation (p = 0.083)." (PMID 24495444, 2014). "Similarly, in prostate cancer, EphA5 downregulation via hypermethylation is linked to a higher tumor grade and invasiveness." (PMID 40806980, 2025). "The patients with mutated EPHA5 exhibited a worse response to atezolizumab treatment, suggesting that EPHA5 mutation might be related to the tumor immune microenvironment." (PMID 36123678, 2022). "Consistent with the present profiling analyses, EPHA4 expression is associated with basal-like BrCa and EPHA5 has been reported to act as a tumor suppressor, which may be related to abrrant promoter methylation." (PMID 33977106, 2021). "Our results revealed the correlation of EPHA5 mutations with tumor immune microenvironment and predictive factors for immunotherapy, implying the potential of EPHA5 mutations as a prognostic marker for the prognosis of LUAD patients to immune checkpoint blockade therapy." (PMID 33288738, 2020). "Given the evidence that EPHA5 mutations were associated with the tumor immune microenvironment, we sought to determine whether EPHA5 mutations are correlated with TMB." (PMID 33288738, 2020). "Although high Ki-67 expression levels were associated with increased EphA5 levels, consistent with its role in tumor proliferation, pAMPK expression was inversely correlated with EphA5 expression, suggesting that metabolic stress may suppress EphA5-mediated pathways." (PMID 40806980, 2025). "MBRC-101 was highly active when tested in patient-derived xenograft (PDX) models of human cancer expressing moderate to high levels of EphA5, potently regressing tumor xenografts relative to controls in all experimental designs." (PMID 40662373, 2025). "EphA5 has been increasingly recognized as a prognostic biomarker in various cancers, with its role varying depending on tumor type." (PMID 40806980, 2025). "The observed positive correlation between EphA5 and Ki-67 expression supports its link to tumor cell proliferation, which is consistent with the established role of Ki-67 as a marker of aggressive tumor biology and poor prognosis in EC." (PMID 40806980, 2025).